SAGE1 (sarcoma antigen 1)
Synonyms: CT14; SAGE
Tractability: PROTAC: UniProt records ubiquitination sites on it.
Gene: Protein-coding gene on chromosome X (135,890,182 to 135,913,062, forward strand). Ensembl gene ENSG00000181433.
Subcellular location: Nucleus
Subcellular location (Human Protein Atlas): Nucleoplasm; Nuclear bodies
Gene Ontology:
Molecular function: protein-macromolecule adaptor activity
Biological process: snRNA 3'-end processing
Cellular component: nuclear body; nucleoplasm; nucleus; integrator complex
Homologues: Orthologues: chimpanzee SAGE1 (98% identical), macaque SAGE1 (46% identical), Drosophila melanogaster IntS6 (8% identical), Caenorhabditis elegans ints-6 (7% identical). Paralogues in human: INTS6L (17% identical), INTS6 (14% identical), CT45A2 (7% identical), CT45A8 (7% identical), CT45A9 (7% identical), CT45A1 (7% identical), CT45A3 (7% identical), CT45A5 (7% identical), CT45A6 (7% identical), CT45A7 (7% identical), CT45A10 (7% identical).
Diseases named in the same sentence as SAGE1 in open-access papers:
SAGE1 is named in the same sentence as 19 diseases in open-access papers, as found by Europe PMC text mining. Sharing a sentence is not in itself a finding about the gene and the disease. The quoted sentences say what the papers report.
breast carcinoma (4 papers, 2011 to 2023). "In this study, we investigated the expression of the cancer/testis antigens ADAM2, CALR3 and SAGE1 in lung and breast cancer, the two most frequent human cancers, with the purpose of providing novel therapeutic targets for these diseases." (PMID 26252478, 2015). "We investigated the potential of three previously uncharacterized CT antigens, ADAM2, CALR3 and SAGE1, as targets for treatment of lung and breast cancer." (PMID 26252478, 2015). "Analysis of ADAM2, CALR3, SAGE1 and MAGE-A expression in cohort 1 consistent of 68 breast cancers of different clinical stages." (PMID 26252478, 2015). "We found different CT antigens to be significantly different in their CT expression rate in breast cancer, and GAGE, NXF2 and SAGE1 were rarely expressed even in the ER-negative group." (PMID 21437249, 2011). "There are few studies that report SAGE1 expression in some types of cancer, but there are no studies that examine its role /function in these types or in breast cancer." (PMID 37200388, 2023). "In conclusion, ADAM2, CALR3 and SAGE1 should not be considered targets for treatment of lung and breast cancer." (PMID 26252478, 2015). "Surprisingly, we detected no ADAM2, CALR3 and SAGE1 in the 67 lung cancers (mainly non-small lung cancer) and 189 breast cancers, while MAGE-A proteins were present in 15% and 7–16% of these tumor types, respectively." (PMID 26252478, 2015). "In addition, the three other CT antigens –GAGE, SAGE1 and Nuclear RNA export factor 2 (NXF2), were infrequently or rarely expressed, only in 3.5%, 2.2% and 1.8% of the breast cancer patients, respectively." (PMID 23451156, 2013).
lung carcinoma (3 papers, 2015 to 2024). "We used a set of previously uncharacterized antibodies against the cancer/testis antigens ADAM2, CALR3 and SAGE1 to investigate their expression in a large panel of normal tissues as well as breast and lung cancers." (PMID 26252478, 2015). "Notably, the tumor-specific expression pattern of SAGE1 has been found in several solid cancers, e.g., bladder cancer, lung cancer, and head and neck cancer, highlighting its role as a potential target for cancer immunotherapy." (PMID 38862430, 2024). "To this end, we have identified antibodies suitable for immunostaining of the three novel CT antigens ADAM2, CALR3 and SAGE1, and characterized the expression of these proteins in normal tissues and the two most common types of human malignancies, breast and lung cancer." (PMID 26252478, 2015). "Our results suggest that ADAM2, CALR3 and SAGE1 cancer/testis antigens are not promising targets for immunotherapy of breast and lung cancer." (PMID 26252478, 2015).
head and neck cancer (2 papers, 2020 to 2024). A primary or metastatic malignant neoplasm affecting the head and neck. "SAGE1 has previously been found to be expressed in 35% of prostate cancers, 33% of oesophageal cancers and 26% of ovarian cancers by qPCR analysis, with some limited expression in head and neck cancers." (PMID 32992503, 2020).
melanoma (2 papers, 2015 to 2016). A malignant, usually aggressive tumor composed of atypical, neoplastic melanocytes. "In particular, tumour antigen genes, such PAGE2B (prostate-associated P antigen family, member 2B), sarcoma antigen 1 (SAGE1) and several melanoma-associated antigens are overrepresented in the RGV regions." (PMID 27158822, 2016). "Furthermore, SAGE1 was detected in about 40% of melanoma cell lines, suggesting that this protein may be an interesting target." (PMID 26252478, 2015).
cancer testis (1 paper, 2011). "Transcripts encoding several cancer testis antigens including the SSX family and SAGE1 were ranked among the top 50 discriminators specifically expressed in SS." (PMID 21706474, 2011).
leukemia (1 paper, 2024). A malignant (clonal) hematologic disorder, involving hematopoietic stem cells and characterized by the presence of primitive or atypical myeloid or lymphoid cells in the bone marrow and the blood. "A few studies have also reported the relevance between SAGE1 and leukemia, while the genetic variation of SAGE1 has not been well studied in cancers." (PMID 38862430, 2024).
cancer (11 papers, 2007 to 2025). A tumor composed of atypical neoplastic, often pleomorphic cells that invade other tissues. "SSX proteins and SAGE1 (as well as our control antigen, MAGEA4) are cancer testis antigens encoded by genes that are normally only expressed in human germ cells, trophoblast, and certain tumours." (PMID 21706474, 2011). "Finally, INTS3/SAGE1 regulates transcription by directly interacting with RNA polymerase II, a direct target in the transcription of genes involved in cancer." (PMID 40278293, 2025). "Furthermore, by applying Pindel-TD to data generated from the K562 cancer cell line, we identified a TD located at the seventh exon of SAGE1, providing an explanation for its high expression." (PMID 38862430, 2024). "Higher ICI-4W expression of extracellular matrix (ECM) genes, including trypsinogens (PRSS1 and PRSS2) and matrix metalloproteases, and genes encoding cancer antigens (CTAG2, SAGE1, MAGEA1/A4/A10, POTEE, and PRAME) was significantly associated with ICI resistance and tumor growth during ICI-4W." (PMID 37433281, 2023). "In comparison, GAGE, SAGE1 and NXF2 were only expressed in 3–5% of ER-negative and 0–2% of ER-positive cancers." (PMID 21437249, 2011). "The other three differentially mutated genes, including SAGE1, TRPM3, and ADAMTS7, have not been implicated in HCC, but in some other cancers." (PMID 27246981, 2016).
tumour (7 papers, 2004 to 2026). "In the region closer to the overt SS, the expression of SAGE1 appeared to be gradually reduced and was totally undetectable in the cells located in close vicinity of the bulk of the tumour." (PMID 21706474, 2011). "In two of these rare cases, we identified spatial differences of SSX2-4 and SAGE1 expression in different subpopulations of ISS cells, with the invasive tumour expressing only SSX antigen." (PMID 21706474, 2011). "Most tumours (32; 89%) were positive for SSX2-4 and amongst these, 14 (39%) were positive for SAGE1." (PMID 21706474, 2011). "In addition, SAGE1 was identified in a subset of SSX2-4-expressing SSs, indicating an origin from the same cell type but potentially at a different stage of tumour progression." (PMID 21706474, 2011).
SAGE1 also shares sentences with these, for which no sentence is quoted: asthma (1 paper); bladder cancer (1); infection (1); non-small cell lung carcinoma (1); oesophageal cancers (1); ovarian carcinoma (1); Pleural effusion (1); prostate carcinoma (1); seminoma (1); spermatocytic seminoma (1); synovial sarcoma (1).